UOX (urate oxidase (pseudogene))
Synonyms: UOXP
Gene: Transcribed unitary pseudogene on chromosome 1 (84,365,428 to 84,397,831, reverse strand). Ensembl gene ENSG00000240520.
Diseases named in the same sentence as UOX in open-access papers:
UOX is named in the same sentence as 7 diseases in open-access papers, as found by Europe PMC text mining. Sharing a sentence is not in itself a finding about the gene and the disease. The quoted sentences say what the papers report.
hyperuricemia (9 papers, 2017 to 2025). An abnormally high level of uric acid. "Urate oxidase (uricase) encoded by UOX gene is a key enzyme whose disfunction causes hyperuricemia." (PMID 35269691, 2022). "Although urate is then catalyzed by uricase, also known as urate oxidase (UOX), to allantoin in most mammals, uric acid is the end product of purine metabolism in humans due to two dysfunctional variants in the UOX gene and is considered a cause of hyperuricemia and gout in humans." (PMID 38137389, 2023). "UOX is an enzyme that catalyzes the oxidation of uric acid and is used as treatment for acute hyperuricemia." (PMID 38265873, 2024). "Urate oxidase (UOX) that catalyzes the enzymatic oxidation of uric acid into allantoin, is effective in lowering plasma uric acid levels and controlling hyperuricemia." (PMID 33639683, 2021). "At least partly due to their increased metabolic rate, UOX knockout in mice results in extreme hyperuricemia and is highly lethal, while it is generally benign in humans (who are all UOX knockouts)." (PMID 30837873, 2019). "In our study, using UOx KO mice, which have been reported as a suitable model of hyperuricemia and more closely mimic purine metabolism in humans, we provided the evidence that serum and striatal urate levels were significantly elevated." (PMID 29434538, 2018). "Therefore, in this study, we investigated one-pot enzyme-nanozyme cascade reactions using urate oxidase (UOX) and catalase-mimic gold nanoparticle nanozyme (AuNP) with the ultimate goal of treatment of hyperuricemia." (PMID 28287162, 2017). "By comparing the important genes involved in urate production, including XOR, UOX, URAH, and URAD, we concluded that chickens are a preferred animal for the hyperuricemia model." (PMID 32245084, 2020).
gout (4 papers, 2022 to 2023). A condition characterized by painful swelling of the joints, which is caused by deposition of urate crystals. "Humans are sensitive to developing gout because they lack a functional urate-metabolizing enzyme called uricase/urate oxidase (encoded by the UOX gene)." (PMID 36553446, 2022). "When urate oxidase (UOX) or HRP was loaded in polymersomes equipped with OmpF pores, the detoxification of uric acid and prevention of H2O2 accumulation took place in kidney-derived HEK293T cells as a first step towards the treatment of gout and oxidative stress." (PMID 35628527, 2022).
Hepatic steatosis (2 papers, 2018 to 2022). Steatosis is a term used to denote lipid accumulation within hepatocytes. "We have also confirmed that UOX-KO mice had hepatic steatosis." (PMID 36177037, 2022).
dyslipidemia (1 paper, 2025). "We found that the pathological features of diabetic hamsters with hyperuricemia and dyslipidemia included urate deposition and renal tubular dilation, degeneration and atrophy, which were similar to those observed in UOX-KO rats, although no fibrotic damage was observed." (PMID 41012372, 2025).
infection (1 paper, 2022). The state of being infected such as from the introduction of a foreign agent such as serum, vaccine, antigenic substance or organism. "Upon infection of tea plant with C. camelliae, we observed alterations in the expression of fungal transcripts, including those of many genes associated with caffeine metabolism, such as those encoding various transporters, xanthine dehydrogenase, and urate oxidase (UOX)." (PMID 36687674, 2022).
UOX also shares sentences with these, for which no sentence is quoted: COVID-19 (1 paper); Nephropathy (1).